MPO (myeloperoxidase)
Diseases named in the same sentence as MPO in open-access papers (continued):
Sharing a sentence is not in itself a finding about the gene and the disease.
vasculitis (continued). "Assessments using Birmingham Vasculitis Activity Score and myeloperoxidase (MPO)‐ANCA assays showed that seven of the nine patients responded to TCZ treatment, and no recurrence was observed in six of these seven patients after TCZ treatment cessation." (PMID 33163184, 2020). "In PR3-ANCA vasculitis, levels of TNF-α, thromboxane A2 (TXA2) and CD14 were increased, while in MPO-ANCA vasculitis the C-C motif chemokine receptor 8 (CCR8) levels was higher and IL-10 expression was lower compared to controls." (PMID 33023023, 2020). "E-selectin is exclusively expressed on endothelial cells, and pro-inflammatory stimuli lead to newly synthesized E-selectin, which is also increased in PR3-ANCA and MPO-ANCA vasculitis." (PMID 33023023, 2020). "In the present study, to determine the diagnostic value of the serum proteasome concentration in antineutrophil cytoplasmic antibody (ANCA)-associated vasculitis (AAV), we investigated patients with myeloperoxidase (MPO)-AAV at various stages of the disease." (PMID 32864569, 2020). "The relationships between sinusitis and relapse of vasculitis and elevated MPO-ANCA levels were assessed using multivariate Cox proportional hazards models that were adjusted for clinically relevant factors." (PMID 33301468, 2020). "On the other hand, patients with PR3-ANCA and MPO-ANCA vasculitis have decreased levels of plasminogen activator inhibitor-1 (PAI-1), which protects endothelial cells from apoptosis and degradation." (PMID 33023023, 2020). "As such, key members such as MMP-3, MMP-9 and tissue inhibitor of metalloproteinase (TIMP)-1 are increased in PR3-ANCA and MPO-ANCA vasculitis." (PMID 33023023, 2020). "The incidence of MPO-AAV is much higher than that of other types of vasculitis in Asian countries, including China and Japan." (PMID 33613528, 2020). "Immunization of mice with a plasmid-encoded peptide with some sequence homology with the T cell immunodominant MPO epitope, but found only in some strains of Staphylococcus aureus, induced anti-MPO autoimmunity and vasculitis." (PMID 32373109, 2020). "MPO-ANCA-associated vasculitis more frequently occurs in Japanese patients, whereas proteinase-3 ANCA-associated vasculitis is more common in Europe and the United States." (PMID 31675941, 2019). "Patients with active vasculitis had the lowest levels, while those with MPO-ANCA vasculitis in remission still had lower levels in comparison to the HC group." (PMID 31640771, 2019). "One patient with AAV had biopsy-proven vasculitis with mononeuritis multiplex and anti-MPO antibodies." (PMID 30764870, 2019). "In vasculitis, myeloperoxidase (MPO) and proteinase-3 (PR3), the two auto-antigens recognized by anti-neutrophil cytoplasm antibodies (ANCA), are, in fact, released from NETs21." (PMID 31138830, 2019). "We confirmed these phenotypic differences, with glomerulonephritis and neuropathy (clinical features consistent with vasculitis) more prevalent in the MPO+ subgroup, whereas lung infiltrates and cardiac involvement were common in the ANCA-negative subgroup." (PMID 31719529, 2019). "In conclusion, the current pathogenic model of AAV suggest that MPO- and PR3-ANCA+ vasculitis share many similar pathogenic features." (PMID 31867013, 2019). "Activation of neutrophils is thought to play a major role in the pathogenesis and this was demonstrated in vivo when a murine disease model of MPO-ANCA vasculitis was established." (PMID 31216309, 2019). "It was demonstrated that serotyping distinguishes distinct classes of ANCA disease: PR3-ANCA associated Vasculitis (PR3-AAV), MPO-ANCA associated Vasculitis (MPO-AAV) and ANCA-negative Vasculitis." (PMID 32185292, 2018). "While murine models demonstrated convincing evidence for MPO-ANCA-induced glomerulonephritis and vasculitis, it has proven extremely difficult to show pathogenicity of PR3-ANCA in vivo." (PMID 29686675, 2018).
vasculitis (continued). "Transfer of these antibodies into wild-type or Rag2 mice (which lack lymphocytes) results in the mice developing severe vasculitis with crescentic GN and pulmonary haemorrhage, demonstrating that MPO-ANCA alone are sufficient to induce disease." (PMID 30079228, 2018). "Anti-neutrophil cytoplasmic antibody (ANCA) vasculitis is characterized by the presence of autoantibodies to myeloperoxidase and proteinase-3, which bind monocytes in addition to neutrophils." (PMID 28138552, 2017). "ANCA‐IgGs were prepared from two patients with active PR3‐ANCA‐positive vasculitis, two patients with active MPO‐ANCA‐positive vasculitis and two healthy volunteers, respectively." (PMID 28181422, 2017). "ANCA-IgG were prepared from two patients with active PR3-ANCA-positive vasculitis, five patients with active MPO-ANCA-positive vasculitis and three healthy volunteers, respectively." (PMID 26739852, 2016). "We induced anti‐myeloperoxidase vasculitis in mice and confirmed a role for complement activation by demonstrating protection in C3‐deficient mice." (PMID 27235854, 2016). "Did we have some clues to doubt the diagnosis of vasculitis in a patient who presented with systemic signs, multiorgan clinical presentations, presence of pulmonary nodules, positive MPO, and signs of vascular damage on open lung biopsy?" (PMID 27293945, 2016). "The finding that the inhibition of NETosis by PTU induces the production of anti-MPO antibodies and vasculitis in rats further supports a protective role of NETosis in autoimmunity." (PMID 27867381, 2016). "We therefore studied properdin‐deficient mice with the aim of confirming and extending our understanding of AP activation in anti‐MPO vasculitis." (PMID 27235854, 2016). "A vasculitis workup resulted in a positive myeloperoxidase anti-neutrophil cytoplasmic antibody (MPO-ANCA)." (PMID 27891268, 2016). "Our discovery cohort comprised 40 patients with systemic vasculitis (cohort 1), and emerged as part of investigation of expression of vasculitis-associated autoantigens (proteinase 3 (PR3), myeloperoxidase, and the associated alloantigen CD177)." (PMID 27227454, 2016). "For example, inhibition of NETosis by propylthiouracil (PTU) induces the production of anti-MPO antibodies and vasculitis in rats, suggesting that the normal process of NETosis is protective against this autoimmune process." (PMID 27867381, 2016). "We modelled the chronic relapsing phenotype of MPO-ANCA vasculitis in an effort to identify urinary metabolites that reflect active inflammation more accurately than measurement of urinary blood and protein." (PMID 27905491, 2016). "In a large proportion of cases, the diagnosis of MPO-ANCA vasculitis was preceded months to years by the diagnosis of PF or signs of interstitial pneumonia." (PMID 26266064, 2015). "In mouse models, T-cell depletion inhibits vasculitis, and a MPO T-cell epitope is essential for glomerular injury." (PMID 25943359, 2015). "Some researchers propose that PR-3 ANCA-associated vasculitis patients are more likely to relapse and display predominant extrarenal manifestations and rapid deterioration of renal function compared to patients with MPO-ANCA vasculitis." (PMID 26236499, 2015). "ANCA-IgG were prepared from two patients with active PR3-ANCA-positive vasculitis, two patients with active MPO-ANCA-positive vasculitis and two healthy volunteers, respectively." (PMID 25889374, 2015). "The major target antigens in patients with vasculitis and glomerulonephritis are myeloperoxidase (MPO) and proteinase 3 (PR3)." (PMID 26688808, 2015). "Half of the patients had positive rheumatoid factor (RhF) at the time of vasculitis diagnosis, three had MPO-ANCA, one PR3-ANCA, and two had ANCA-negative pauci-immune vasculitis." (PMID 25664229, 2015).
vasculitis (continued). "The data presented here offer evidence that the neutrophil MPs-associated myeloperoxidase-hydrogen peroxide-chloride pathway may contribute to endothelial cell lesion and consequently to expand the endothelial cell damage observed in conditions of neutrophil activation such as vasculitis and sepsis." (PMID 24915973, 2014). "On the other hand, vasculitis was proven in five of 15 biopsy specimens of MPO-ANCA-positive patients with pulmonary fibrosis." (PMID 24758294, 2014). "Rats immunised with human MPO develop anti-MPO antibodies that cross-react with human and rat MPO, and thus generate a small-vessel vasculitis." (PMID 25056155, 2014). "ANCA-postive IgG was prepared from three patients with active MPO-ANCA-positive vasculitis and two patients with active PR3-ANCA-positive vasculitis, respectively." (PMID 25000985, 2014). "In the present study, 58.4% of sera from patients with MPO-ANCA positive vasculitis recognized one or more linear epitopes on MPO molecule." (PMID 23577119, 2013). "Accordingly, it is important to distinguish polyarthritis as a side effect of MMI from MPO-ANCA vasculitis." (PMID 24379039, 2013). "As expected, due to the milder vasculitis phenotype in Ccr2−/− mice, serum MPO level post-injection in these mice was lower than in Ccr2+/+ mice." (PMID 23074996, 2012). "First, previous studies that investigated the role of the complement system in the pathogenesis of AAV focused mainly on MPO-ANCA-positive vasculitis." (PMID 22691190, 2012). "Deposition of NETs initiates inflammatory response in the kidney, while in individuals with small-vessel vasculitis circulating MPO-DNA complexes triggered vasculitis and promoted autoimmune response." (PMID 23110185, 2012). "In an anti-MPO antibody-induced mouse vasculitis model, ANCA and neutrophils are necessary for the initiation of glomerulonephritis." (PMID 22675451, 2012). "It was shown that WG patients during ATD therapy changed PR3-ANCA to MPO-ANCA with flares of vasculitis." (PMID 16207324, 2005). "Microscopic polyangiitis (MPA) is a rare form of vasculitis associated with anti-neutrophil cytoplasmic antibodies (ANCA), most commonly myeloperoxidase (MPO)-ANCA, and can present with multi-organ involvement, most frequently affecting the kidneys, lungs, and skin." (PMID 41446683, 2026). "Moreover, the patient had P-Anti Neutrophil Cytoplasmic Antibody and Myeloperoxidase antibodies (indicative of vasculitis)." (PMID 41226731, 2025). "Our findings also highlight the importance of ongoing surveillance of MPO‐antibody titres and clinical features of vasculitis on follow‐up, as MPO‐antibody positivity and features of MPA‐ILD may manifest many years later." (PMID 40641494, 2025). "We identified patients with hydralazine-associated ANCA vasculitis, nonhydralazine-associated ANCA vasculitis with high-titer MPO-ANCA serologies, and people who were in a healthy control group." (PMID 40020049, 2025). "All animals immunized with MPO developed signs of vasculitis." (PMID 40821760, 2025). "Similarly, components within NETs, such as myeloperoxidase (MPO) and proteinase 3, are also key target antigens in anti-neutrophil cytoplasmic antibody (ANCA)-associated vasculitis." (PMID 41459159, 2025). "These patients exhibited elevated anti-MPO IgM levels, while anti-MPO IgG levels were comparable between hydralazine-associated and nonhydralazine-associated vasculitis patients." (PMID 40020049, 2025). "Moreover, SLE is even known to have a complication such as MPO-specific antineutrophil cytoplasmic antibody (ANCA) vasculitis." (PMID 41465552, 2025). "Continuing with the example of the AAV mouse model, where many current models rely on anti-MPO induction of vasculitis, an improvement would be to generate mice expressing human MPO or PR3, the primary targets of ANCA, to better mimic the progression of human disease." (PMID 40429915, 2025).
vasculitis (continued). "Compared with ANCA-negative vasculitis cases, the adjusted odds of participants having kidney involvement were 7.8 (95% CI 3.4 to 18.5, p<0.001) and 3.3 (95% CI 1.6 to 6.6, p<0.001) times higher in individuals with MPO-ANCA and PR3-ANCA, respectively." (PMID 38886004, 2024). "The objective of this study was to determine whether serum ceruloplasmin level at diagnosis had a prognostic impact in patients with anti-MPO antibody-positive vasculitis." (PMID 39388433, 2024). "Therefore, future studies should focus on the activated common immunological pathways and gene expression profiles between MIS-C and MPO-ANCA vasculitis patients." (PMID 39280366, 2024). "Antineutrophil cytoplasmic antibody (ANCA)-associated vasculitis (AAV) is a group of complex autoimmune diseases characterized by the vasculitis, endothelial injury, and tissue damage as well as the presence of serum autoantibodies targeting myeloperoxidase (MPO-ANCA) or proteinase 3 (PR3-ANCA)." (PMID 38578316, 2024). "Patient 2: A 52-year-old male patient was admitted to our clinic with a creatinine increase as well as active urinary sediment after six pulses of i.v. cyclophosphamide, because of recently diagnosed MPO-ANCA positive vasculitis with extensive organ manifestations." (PMID 39300109, 2024). "The Vasculitis Clinical Research Consortium confirmed these associations and provided the first evidence for genetic variants, such as those in PTPN22, common to both PR3-AAV and MPO-AAV." (PMID 38791316, 2024). "Furthermore, due to the small group size, it is challenging to conduct separate analyses for MPO-ANCA-associated and PR3-ANCA-associated vasculitis." (PMID 39304942, 2024). "Another study further corroborated the finding that the pathogenicity of MPO–ANCA in vasculitis is determined by epitope specificity, explaining why natural MPO autoantibodies exist in healthy individuals and why ANCA titers do not always correlate with disease activity." (PMID 39456878, 2024). "The presentation of MPO-ANCA vasculitis as ILD can be the first and only clinical manifestation." (PMID 38445024, 2024). "Previous work has suggested that neutrophil serine proteases are required in anti-MPO vasculitis." (PMID 36154801, 2023). "Mice with inactive PI3Kδ were protected from anti‐MPO vasculitis." (PMID 35818684, 2023). "Here, we assessed if myeloid-specific Mcl1 was required in murine anti-myeloperoxidase vasculitis and whether inhibition of myeloperoxidase was protective." (PMID 36154801, 2023). "This experimental design meant that in each recipient mouse with anti‐MPO vasculitis, we could assess the relative recruitment to the kidney of adoptively transferred wild‐type and D910A monocytes." (PMID 35818684, 2023). "Anti-MPO vasculitis was induced as before in 2 groups of mice that were given AZD5904 or control." (PMID 36154801, 2023). "Anti‐MPO vasculitis was induced in mice with inactive p110δ (D910A) and in wild‐type mice." (PMID 35818684, 2023). "The optimal strategy for remission-maintenance therapy in patients with myeloperoxidase-ANCA (MPO-ANCA)–associated vasculitis is not established." (PMID 36526414, 2023). "However, proteinase 3-ANCA (PR3-ANCA) and MPO-ANCA have been found in most vasculitis patients, both characteristic of AAV pathogenesis." (PMID 35409152, 2022). "The raised levels of complement factors in the supernatant and the increased C5 expression of ANCA-activated neutrophils demonstrated that S100A8/A9 and S100A12 could promote the activation of the alternative complement pathway in MPO-ANCA-positive vasculitis." (PMID 36088289, 2022). "C4-deficient mice are not protected against vasculitis induced by transfer of anti-MPO antibodies, whereas C5 deficiency confers protection." (PMID 33451011, 2021). "This could be explained by the fact that patients with MPO-ANCA(+) have poorer renal outcomes, worse renal disease, they are more HD dependent, and have more chronic lesions in kidney biopsy than MPO-ANCA(+) vasculitis." (PMID 35127750, 2021).
vasculitis (continued). "Vasculitis classification, severity, and treatment in MPO-AAV patients." (PMID 33481903, 2021). "V-Type immunoglobulin domain-containing suppressor of T-cell activation (VISTA)-deficient mice were protected in the nephrotoxic nephritis model but the role of VISTA in anti-myeloperoxidase vasculitis is unknown." (PMID 36751530, 2021). "Indeed, only 7–23% of ANCA-positive subjects subsequently developed a clinically overt vasculitis during the follow-up, mainly limited to patients with anti-MPO antibodies." (PMID 34207641, 2021). "Afterward, many authors suggested an association between IPF and anti-MPO antibodies, regardless of the occurrence of vasculitis, mainly micro-polyangiitis (MPA)." (PMID 34207641, 2021). "One autoimmune disease where neutrophils play important roles is MPO-ANCA Microscopic Vasculitis." (PMID 33790907, 2021). "Overall, research should focus on differences among patients with PR3-ANCA and MPO-ANCA vasculitis." (PMID 33023023, 2020). "In addition, MCP-1 is involved in attraction of monocytes and macrophages at the site of inflammation and several studies provided evidence that urinary MCP-1 is elevated in PR3-ANCA and MPO-ANCA vasculitis." (PMID 33023023, 2020). "A vasculitis workup resulted in a high antimyeloperoxidase (MPO) antibody level." (PMID 33489567, 2020). "In contrast, IL-17A and IL-23 are elevated in both, PR3-ANCA and MPO-ANCA vasculitis." (PMID 33023023, 2020). "In addition, a case of maternal–fetal transmission of anti-MPO ANCA with development of vasculitis in the newborn has been described." (PMID 33372616, 2020). "Both IL-1β and ROS have been shown to result in tissue damage which may help drive the glomerulonephritis that is observed in some patients with MPO-ANCA vasculitis." (PMID 33015103, 2020). "Interestingly, the presence of PR3- and MPO-ANCA have led to the differentiation of distinct disease phenotype of AAV: PR3-ANCA-associated vasculitis (PR3-AAV), MPO-ANCA-associated vasculitis (MPO-AAV), and ANCA-negative vasculitis." (PMID 31544837, 2019). "However, MPO-ANCA-positive cases involve vasculitis of the arterioles and capillaries, and are therefore diagnosed as microscopic polyangiitis." (PMID 30850017, 2019). "In this retrospective single centre study we have focused the analysis only in the subgroup of MPO vasculitis with severe renal involvement, because of scarce data in the use of RTX in these patients and the likely increased effectiveness of RTX in PR3 disease, as reported by some authors." (PMID 31088509, 2019). "Indeed, the pathogenic potential of ANCAs has been demonstrated in a mouse model of vasculitis induced by anti-MPO antibodies." (PMID 31248381, 2019). "In this study, IgG purified from patients with ANCA-negative vasculitis was able to bind to an MPO epitope, and it was suggested that competition for binding in immunoassays by a fragment of caeruloplasmin may be why ANCA cannot be detected in these patients." (PMID 30079228, 2018). "Similar to other inflammatory conditions renal-limited MPO-ANCA vasculitis may involve more tissue-restricted inflammatory processes compared to ANCA-negative and PR3-ANCA CPV, which may depend on circulating or vessel-associated immune cell activation." (PMID 30533405, 2018). "Of the patients eight had peripheral arterial occlusive disease (PAOD) Fontaine stage IV and concomitant DFS, one female patient had extensive vasculitis (MPO [myeloperoxidase], p‐ANCA, cryo-positive) of small, medium, and large vessels in the setting of undifferentiated collagenosis." (PMID 30147244, 2018). "Genome-wide association studies (GWAS) have shownd that HLA-DP (rs3117242) variants contribute to the pathogenesis of MPO-ANCA associated vasculitis, while PRTN3 (rs 62,132,295) variants might contribute to PR3-ANCA associated vasculitis." (PMID 30286799, 2018). "There is increased NET formation in both MPO-ANCA vasculitis and SLE." (PMID 29435367, 2017).